GLP1R (glucagon like peptide 1 receptor)
Diseases named in the same sentence as GLP1R in open-access papers (continued):
Sharing a sentence is not in itself a finding about the gene and the disease.
diabetes (continued). "In humans, dual GLP‐1R/GCGR agonism is thought to result in additive effects of reducing food intake and lowering glucose levels, making this an attractive approach for weight management in individuals with diabetes." (PMID 34713962, 2022). "A previous study demonstrated that the phosphorylation of eNOS at Ser-1177 could be stimulated by the activation of the GLP-1 receptor (GLP-1R) in HUVECs to produce NO, which may be involved in improving atherosclerosis in diabetes." (PMID 36354682, 2022). "Since this study enrolled patients (from the registry) from 2005, many patients with diabetes did not experience the benefits of newer therapies (such as sodium–glucose cotransporter 2 inhibitor, glucagon-like peptide-1 receptor agonist)." (PMID 36079008, 2022). "Importantly, GLP-1 is not the only incretin involved in the pathogenesis of bone fragility in diabetes, with single GIP receptor (GIPR) KO and dual GLP-1R/GIPR KO mice presenting with enhanced bone fragility." (PMID 34093449, 2021). "Current investigation into the usage of established diabetes drugs in the management of PD is now under trial including sodium-glucose cotransporter 2 (SGLT2) inhibitors, glucagon-like peptide-1 receptor agonists (GLP-1RA), and dipeptidyl peptidase-4 (DPP-4) inhibitors." (PMID 34943038, 2021). "Designing drugs with the optimal combination of GLP-1R and GCGR activation is important and may confer greater benefits in reversing diabetes than GLP-1R activation alone, as demonstrated recently." (PMID 34572144, 2021). "In light of their already beneficial utility in the management of diabetes, the use of NLY01 and other GLP-1R agonists is particularly promising in their potential for the treatment of PDR, the leading cause of blindness in working-age adults in developed countries worldwide." (PMID 34673570, 2021). "Dulaglutide, a glucagon-like peptide-1 receptor (GLP-1R) agonist, is widely used to treat diabetes." (PMID 34537761, 2021). "Moreover, as a novel agonist of glucagon-like peptide-1 receptor (GLP-1R), GEN also has a role in the treatment of diabetes and diabetic complications." (PMID 34938383, 2021). "Recent studies have reported that some anti-diabetes drugs may have beneficial effects in HF, including dipeptidyl peptidase-4 (DPP-4) inhibitors, glucagon-like peptide-1 receptor agonists (GLP-1 RAs), and SGLT-2 inhibitors." (PMID 34759887, 2021). "Are there circumstances in which a switch in GLP-1R coupling from Gαs to Gαq is of physiologic importance (as opposed to pathologic, i.e., diabetes mellitus)." (PMID 33935974, 2021). "We previously found that the activation of microglial glucagon-like peptide 1 receptor (GLP-1R) could potently relieve formalin-, bone cancer-, peripheral nerve injury-, and diabetes-induced pain hypersensitivity." (PMID 34512747, 2021). "In this present work, we detected up-regulated RAGE and down-regulated GLP-1R in hippocampus of mice with diabetes compared with non-diabetic mice." (PMID 33298623, 2020). "Glucagon like peptide 1-receptor agonists (GLP-1) and sodium glucose co-transporter 2 inhibitors (SGLT2) may improve cardiovascular outcome, in patients with diabetes mellitus and cardiovascular disease." (PMID 33143256, 2020). "Collectively, the findings from these studies suggest that both DPP-4 inhibitors and GLP-1R agonists exert beneficial actions on EDH in diabetes through mechanisms independent of their glucose-lowering effects." (PMID 31370156, 2019). "The GLP-1R-cAMP pathway also decreases islet inflammation leading to better survival of β-cells, and macrophage infiltration and inflammation of adipose tissue are inhibited by GLP-1 in an obese mouse model of diabetes." (PMID 31708773, 2019). "In our study, we hypothesized that off-target interactions of specificdrugs with gut hormone receptors GLP1R, GIPR and GCGR could be a way to compensate for the negative influence of each on glucose homeostasis leading to drug-induced diabetes." (PMID 30682072, 2019).
diabetes (continued). "In the retinas of diabetic db/db mice, GLP-1 expression was decreased, while, similar to findings in diabetic patients without PDR, GLP-1R expression seemed to be unaffected by diabetes." (PMID 31374938, 2019). "Higher expression of GLP-1R was found in OMAT of obese insulin-resistant subjects when compared with subjects with low insulin resistance, however, we were not able to reproduce these findings in morbidly obese subjects of whom most had diabetes." (PMID 27941938, 2016). "Liraglutide, a glucagon-like peptide-1 receptor (GLP-1R) agonist, is widely used to treat diabetes." (PMID 27581840, 2016). "Our recent findings suggested that the glucagon-like peptide 1 receptor (GLP-1R) may be involved in at least part of obestatin activities, implying therapeutic potential in metabolic dysfunctions and diabetes." (PMID 23741322, 2013). "Exendin-4, the naturally occurring form of exenatide, was investigated as a potential ligand for the GLP-1R and a possible diabetes therapy after a number of nonclinical discoveries." (PMID 23256660, 2013). "· Activation of both GLP-1R and GIPR is known to stimulate insulin synthesis and insulin release, and both receptors have therefore been suggested as potential targets for the treatment of diabetes." (PMID 23110768, 2012). "Given that GLP-1R agonists are crucial medications for treating diabetes, identifying the signaling pathways and mechanisms involved in the response to GLP-1R agonists could have significant implications for diabetes therapy." (PMID 41480766, 2026). "Glucagon-like peptide-1 receptor agonists (GLP-1RAs) and sodium-glucose cotransporter 2 inhibitors (SGLT-2is) have been shown to provide extra-glycemic advantages, such as cardiovascular and renal protection, in the treatment of type 2 diabetic mellitus (T2DM)." (PMID 41409228, 2025). "Notably, glucagon-like peptide-1 receptor agonists (GLP-1RAs), including widely used agents such as Ozempic, have demonstrated the ability to elevate adiponectin levels while improving metabolic and inflammatory profiles in patients with obesity and diabetes." (PMID 40652274, 2025). "Multiple recent observational studies have demonstrated an association between glucagon-like peptide-1 receptor agonist (GLP-1 RA) use, particularly semaglutide, and reduced incidence and recurrence of SUDs among individuals with diabetes, regardless of prior SUD history." (PMID 41287656, 2025). "From a multi-target perspective, the elevation in cAMP levels may not solely result from GLP-1R activation but could also involve other diabetes-related therapeutic targets such as DPP4, GIPR, and GCGR." (PMID 41373699, 2025). "Clinical studies and meta-analyses show that approved GLP-1R agonists (liraglutide, semaglutide, tirzepatide) induce a significant reduction in body weight in adults with obesity or overweight, both with and without diabetes." (PMID 41303737, 2025). "With recent success on the market, there is no doubt that GLP-1R agonist may soon significantly modify diabetes and obesity." (PMID 38915346, 2024). "Medications such as Sodium-Glucose Cotransporter 2 inhibitor (SGLT2i), Glucagon-Like Peptide 1 Receptor Agonist (GLP-1RA), and the novel dual glucose-dependent insulinotropic polypeptide (GIP) and GLP-1 receptor agonist, tirzepatide, have revolutionized diabetes treatment paradigms." (PMID 39335551, 2024). "Sodium-glucose co-transporter-2 inhibitors (SGLT2Is) and glucagon-like peptide-1 receptor agonists (GLP-1RAs) are antihyperglycemic agents that were approved by the U.S. Food and Drug Administration (FDA) in 2013 and 2012, respectively, for the treatment of non-insulin-dependent diabetes mellitus." (PMID 38659524, 2024). "In summary, from our summary of the current status of GLP-1R molecular imaging in endocrinology, we realize that quantification of BCM in diabetes and islet transplantation may be the last winner and that current advances in molecular medicine in this field are full of promise." (PMID 37780209, 2023).
diabetes (continued). "However, patients with diabetes with VSG develop only modest glucose intolerance when treated with the GLP-1R antagonist exendin-, similar to a non-operated control group." (PMID 36875493, 2023). "Metformin and liraglutide, a glucagon-like peptide 1 receptor (GLP1R) agonist, are the most commonly used drugs to treat obese patients with diabetes mellitus (DM) and pre-diabetes." (PMID 36614074, 2022). "On the other hand, different diabetes drugs, such as metformin, thiazolidinediones (TZD), glucagon-like peptide-1 receptor (GLP-1R) agonists, dipeptidyl peptidase-4 (DPP-4) inhibitors, and sodium-glucose cotransporter (SGLT2) inhibitors, could be used as treatment strategies for PCOS." (PMID 36588716, 2022). "Diabetes mellitus is characterized by increased inflammation, reflecting innate immune control disorders, and studies have shown a local intestinal intraepithelial lymphocyte (IEL)-GLP-1 receptor (GLP-1R) signaling network that controls the mucosal immune response." (PMID 36569936, 2022). "Given the early findings and pharmacological superiority of GLP-1R agonists in neurological pathophysiology, we hypothesized that GLP-1R activation could inhibit pyroptosis of microglia, subsequently reducing neuroinflammation in diabetes with depression." (PMID 36615696, 2022). "Advances in GLP-1R-targeted imaging have opened the door to non-invasive BCM quantification in the whole intact pancreas, representing a breakthrough in uncovering the pathophysiology of diabetes mellitus and guiding the development of novel therapeutic strategies in diabetes." (PMID 34248856, 2021). "It was originally thought that some anti-diabetes treatment (such as metformin, PPARs, DPP4 inhibitors, GLP-1R agonists, SGLT2 inhibitors and insulin therapy) could influence the course of COVID-19; however, no convincing evidence has emerged to support this view." (PMID 33335527, 2020). "Imaging diagnostics using exendin based analogues targeted at GLP-1R in combination with SPECT and PET has proven its clinical value in insulinoma management, while many potential clinical uses in metabolic diseases including diabetes and islets transplantation are under investigation." (PMID 31903131, 2020). "Diabetes drug use status after TBIR treatment was as follows for 17 cases (with duplicate use): 8 cases had no prescription, 6 cases used α-glucosidase inhibitors, 3 cases used glucagon-like peptide-1 receptor agonists, 2 cases used insulin, and 2 cases used biguanide." (PMID 32337291, 2020). "Nevertheless, the first peptidic GLP1R agonist to be used as a drug was approved by FDA in 2005 (exenatide—Byetta) and still the number of small-molecule non-peptidic compounds targeting incretin hormone receptors to treat diabetes and obesity is extremely small." (PMID 30650080, 2019). "In this work, we examined the expression of the GLP-1R in an incretin target organ, namely, the stomach in chemical and nutrient induced experimental diabetes, in order to elucidate the mechanisms of possible differences in GLP-1R expression in diabetes mellitus with different etiopathogenesis." (PMID 25893200, 2015). "Boc5 may produce metabolic benefits via multiple synergistic mechanisms and may represent an attractive tool for therapeutic intervention of obesity and diabetes, by means of non-peptidic GLP-1R agonism." (PMID 21151924, 2010). "Emerging therapeutic paradigms in diabetes mellitus (DM) leverage the pleiotropic benefits of sodium-glucose cotransporter-2 inhibitors (SGLT-2Is) and glucagon-like peptide-1 receptor agonists (GLP-1RAs), extending beyond glycemic control to systemic immunomodulation." (PMID 41208872, 2025). "Furthermore, we showed the antihypertensive effect of GLP-1R agonist in addition to and independently of well-established anti-diabetic and anti-obese effects, suggesting that GLP-1R agonist is beneficial especially to the hypertensive patients with diabetes and/or obesity." (PMID 31537818, 2019).
diabetes (continued). "Therefore, it is possible that the GLP-1R reduced expression precedes the pathomorphological changes and may serve as additional marker of early extrapancreatic cellular damage induced by STZ diabetes." (PMID 25893200, 2015). "However, as GLP-1R expression is generally absent in most tumor specimens, the anticancer effects of Ex-4 may be restricted to specific patients with ovarian cancer who also have diabetes." (PMID 40140925, 2025). "Our results are consistent with previous studies on the efficacy and safety of the GLP-1R agonists and GCGR dual agonists for the treatment of obesity and overweight in individuals with and without diabetes." (PMID 38440786, 2024). "In 2021, reports from the Semaglutide Treatment Effect for People with Obesity (STEP) trials provided evidence of the effect of semaglutide, a glucagon-like peptide-1 receptor agonist (GLP-1 RA), on reducing body weight in patients without diabetes." (PMID 36769420, 2023). "Glucagon-like peptide-1 receptor agonists (GLP1RA) have been shown to improve glucose control and diabetes-related comorbidities in patients without solid organ transplants." (PMID 32095510, 2020). "While anti-IL-21 monotherapy potently prevents diabetes in the NOD model, it does not reverse.It was therefore opted to combine the GLP-1R agonist liraglutide with anti-IL-21, resulting in reversal after hyperglycemia onset in the NOD model." (PMID 30356664, 2018). "Since Glp-1R agonists or analogues have not been tested in diabetic subjects with gastric or duodenal ulcers, the results of this study may provide fundamental evidence for the subsequent comparative studies between different antipeptic ulcer therapies in diabetes." (PMID 29095895, 2017). "Finally, patients with diabetes in our study might not have used newer hypoglycemic agents protective against CVD events, such as sodium-glucose cotransporter 2 inhibitors or glucagon-like peptide-1 receptor agonists." (PMID 38422102, 2024). "Therefore, it is possible that the relative activity of tirzepatide at the GLP-1R and GIPR may vary in subjects with and without diabetes as well as with the degree of hyperglycemia." (PMID 37277609, 2023).
Obesity (1,328 papers, 2010 to 2026). Accumulation of substantial excess body fat. "Glucagon-like peptide-1 receptor agonists (GLP-1RAs) have transformed the management of obesity by producing substantial and durable weight loss." (PMID 42106160, 2026). "Glucagon-like peptide-1 receptor agonists (GLP-1RAs) have reshaped obesity management by producing clinically meaningful weight loss, primarily through appetite suppression and reduced energy intake." (PMID 41953539, 2026). "Glucagon-like peptide-1 receptor agonists (GLP-1RAs) have transformed obesity treatment, achieving weight loss previously considered attainable only with bariatric surgery." (PMID 41948476, 2026). "Survodutide is a novel GCG/GLP-1 receptor (GCGR/GLP-1R) dual agonist in clinical development for people with obesity and people with metabolic dysfunction-associated steatohepatitis (MASH)." (PMID 41638399, 2026). "A recent retrospective cohort study compared the effects of GLP-1R agonists versus bariatric surgery on the risk for obesity-associated cancers." (PMID 41178720, 2025). "The potential exists for GLP-1R–targeted therapies to substantially reduce the global burden of obesity-associated diseases, including cancer." (PMID 41178720, 2025). "Supporting this, preclinical models of diet-induced obesity showed blunted GLP-1R-mediated weight loss following experimental MS." (PMID 40475994, 2025). "Semaglutide and Liraglutide, developed as long-acting GLP-1R agonists, have shown dramatic weight loss effects in treating metabolic disorders, including obesity and type 2 diabetes." (PMID 39974186, 2025). "On the other hand, glucagon-like peptide-1 receptor agonists (GLP-1RAs) represent a newer group of medications used to treat obesity, showing significant potential in supporting weight loss for individuals struggling with this condition." (PMID 41011232, 2025). "The advent of novel glucagon-like peptide-1 receptor agonists (GLP1RA) has transformed obesity management, achieving weight loss outcomes that approach those of bariatric procedures." (PMID 41284989, 2025). "Deficiency of GLP-1R signaling, therefore, contributes to weight gain and obesity by increasing appetite." (PMID 41328144, 2025). "The findings to date indicate that GEP44 is a promising drug that overcomes the adverse side effects associated with existing GLP-1R agonist medications to treat obesity and/or T2DM." (PMID 39829931, 2025). "A recent therapeutic advance has been the approval of peptides targeting the glucagon-like peptide-1 (GLP-1) receptor (GLP-1R) for obesity and weight loss." (PMID 40835007, 2025). "The leading search terms were clinical trials, obesity phenotypes, incretins, glucagon-like peptide-1 receptor antagonists, nutraceuticals and diet and their association with cardiovascular risk and prevention of CVD." (PMID 40282955, 2025). "It should be noted that GIPR antagonism paradoxically produces additive weight loss when paired to GLP-1R agonism in preclinical studies and that this mechanism appears relevant in patients with obesity." (PMID 39963285, 2025). "The recent recommendations for GLP-1R agonists and GLP-1R-GIPR co-agonists for use in obesity have caused a global increase in their prescription and, thus, spending." (PMID 41464694, 2025). "Glucagon-like peptide-1 receptor agonists (GLP-1RAs) have emerged as effective treatments for obesity, achieving 15–25% weight loss while improving glycemic control, cardiovascular outcomes, and hepatic metabolism." (PMID 41462691, 2025). "This decision analytical model projects changes in obesity-related cancer incidence among US adults following the potential impact of glucagon-like peptide 1 receptor agonists on weight loss." (PMID 40920384, 2025). "Together, these studies indicate that GLP-1R therapies inhibit breast cancer growth, potentially through mechanisms unrelated to weight loss or obesity." (PMID 41178720, 2025).